DICER1 (dicer 1, ribonuclease III)
Description:
Double-stranded RNA (dsRNA) endoribonuclease playing a central role in short dsRNA-mediated post-transcriptional gene silencing. Cleaves naturally occurring long dsRNAs and short hairpin pre-microRNAs (miRNA) into fragments of twenty-one to twenty-three nucleotides with 3' overhang of two nucleotides, producing respectively short interfering RNAs (siRNA) and mature microRNAs. SiRNAs and miRNAs serve as guide to direct the RNA-induced silencing complex (RISC) to complementary RNAs to degrade them or prevent their translation. Gene silencing mediated by siRNAs, also called RNA interference, controls the elimination of transcripts from mobile and repetitive DNA elements of the genome but also the degradation of exogenous RNA of viral origin for instance. The miRNA pathway on the other side is a mean to specifically regulate the expression of target genes.
Synonyms: DICER; HERNA; KIAA0928; K12H4.8-LIKE; DCR1; Dicer1e; GLOW; MNG1; RMSE2; aviD
Tractability: PROTAC: ubiquitination databases record sites on it; its protein half-life has been measured.
Target class: Enzyme; Hydrolase
Gene: Protein-coding gene on chromosome 14 (95,086,228 to 95,158,010, reverse strand). Ensembl gene ENSG00000100697.
Subcellular location: Cytoplasm; Cytoplasm, perinuclear region
Subcellular location (Human Protein Atlas): Cytosol
Pathways (Reactome):
Gene expression (Transcription): MicroRNA (miRNA) biogenesis; Small interfering RNA (siRNA) biogenesis; tRNA-derived small RNA (tsRNA or tRNA-related fragment, tRF) biogenesis
Developmental Biology: M-decay: degradation of maternal mRNAs by maternally stored factors; Regulation of MITF-M-dependent genes involved in apoptosis
Gene Ontology:
Molecular function: double-stranded RNA binding; pre-miRNA binding; protein binding; protein domain specific binding; ribonuclease III activity; RNA endonuclease activity; siRNA binding; deoxyribonuclease I activity; RNA binding; ATP binding; nucleic acid binding; regulatory RNA binding; RNA endonuclease activity producing 5'-phosphomonoesters, hydrolytic mechanism
Biological process: global gene silencing by mRNA cleavage; miRNA processing; negative regulation of gene expression; negative regulation of tumor necrosis factor production; negative regulation of tumor necrosis factor-mediated signaling pathway; pre-miRNA processing; RISC complex assembly; siRNA processing; apoptotic DNA fragmentation; miRNA metabolic process; negative regulation of Schwann cell proliferation; negative regulation of transcription by RNA polymerase II; nerve development; neuron projection morphogenesis; peripheral nervous system myelin formation; positive regulation of myelination; positive regulation of Schwann cell differentiation; tRNA decay; post-transcriptional gene silencing; regulation of multicellular organismal process; RNA processing
Cellular component: cytosol; extracellular exosome; perinuclear region of cytoplasm; RISC complex; RISC-loading complex; cytoplasm; nucleus
Genetic constraint (gnomAD): Loss-of-function variants: 41 observed, 193.23 expected, observed/expected ratio (o/e) 0.21, 90% interval 0.16 to 0.28. The upper end of that interval is the gene's LOEUF score, 0.28, which puts it in group 1 of 6, group 1 being the genes least tolerant of losing a copy. Missense variants: 1,565 observed, 2,388.1 expected, observed/expected ratio (o/e) 0.66, 90% interval 0.63 to 0.68. Synonymous variants: 814 observed, 846.4 expected, observed/expected ratio (o/e) 0.96, 90% interval 0.91 to 1.02.
Gene-disease validity (ClinGen):
ClinGen rates the evidence that DICER1 causes each of these diseases.
DICER1-related tumor predisposition (autosomal dominant): Definitive. Pathogenic germline variation in DICER1 confers an autosomal dominant predisposition to tumor formation at multiple primary sites, including pleuropulmonary blastoma, pulmonary cysts, thyroid gland neoplasia, ovarian tumors, and cystic nephroma.
Cancer hallmarks: invasion and metastasis (suppresses); invasion and metastasis (promotes or suppresses); angiogenesis (suppresses); escaping programmed cell death (promotes); proliferative signalling (promotes); genome instability and mutations (suppresses); cell replicative immortality (suppresses); escaping programmed cell death (suppresses)
Homologues: Orthologues: chimpanzee DICER1 (99% identical), macaque DICER1 (98% identical), dog DICER1 (97% identical), guinea pig DICER1 (96% identical), pig DICER1 (94% identical), rat Dicer1 (93% identical), mouse Dicer1 (93% identical), tropical clawed frog dicer1 (82% identical), zebrafish dicer1 (79% identical), Drosophila melanogaster Dcr-1 (39% identical), Caenorhabditis elegans dcr-1 (36% identical).
Diseases named in the same sentence as DICER1 in open-access papers:
DICER1 is named in the same sentence as 382 diseases in open-access papers, as found by Europe PMC text mining. Sharing a sentence is not in itself a finding about the gene and the disease. The quoted sentences say what the papers report.
pleuropulmonary blastoma (76 papers, 2012 to 2025). A malignant neoplasm affecting the lungs and/or the pleura. "Pathogenic DICER1 variants were found in 70% of patients with all types of pleuropulmonary blastoma (PPB) and have also been reported in other neoplasms." (PMID 40069796, 2025). "A patient diagnosed with pleuropulmonary blastoma was found to carry a pathogenic DICER1 mutation, confirming a genetic predisposition identified through germline DNA sequencing." (PMID 40868080, 2025). "The mutation status of DICER1 alleles was determined in a cohort of patients diagnosed with pleuropulmonary blastoma." (PMID 39857323, 2025). "Thyroid disorders associated with DICER1 have drawn increasing attention since 2009, when the first report of a DICER1 mutation in pleuropulmonary blastoma (PPB) was published." (PMID 41104964, 2025). "Since the first association between pleuro-pulmonary blastoma and DICER1 alterations in 2009, many tumor histotypes have been characterized by somatic and/or germline DICER1 pathogenic variants." (PMID 40448797, 2025). "Common DICER1-associated tumors include pleuropulmonary blastoma, ovarian Sertoli-Leydig cell tumor, and various thyroid diseases such as papillary, follicular, poorly differentiated carcinomas, and multinodular goiter." (PMID 40007992, 2025). "In research involving eleven patients with spontaneous pleuropulmonary blastomas and DICER1 gene mutations, eight of the patients had biallelic DICER1 gene mutations, with one mutation located in the RNase IIIb domain." (PMID 39857323, 2025). "An association has been discovered between CBME and pleuropulmonary blastoma (PPB)—a rare pediatric lung malignancy most frequently occurring in individuals with DICER1 mutation." (PMID 40150037, 2025). "The association between germline DICER1 pathogenic variants and pleuropulmonary blastoma (PPB) in the lung is well known." (PMID 39847050, 2025). "The gold standard for definitive diagnosis is histopathological and immunohistochemical analysis, with molecular and genetic studies, such as DICER1 mutation screening in pleuropulmonary blastoma, increasingly used to refine diagnosis." (PMID 40217628, 2025). "A germline mutation of the DICER1 gene causes the rare eponymous autosomal dominant syndrome predisposing the development of multiple tumor types, e.g., pleuropulmonary blastoma, cystic nephroma, and ovarian SLCT." (PMID 39336518, 2024). "Dicer1 syndrome is a rare genetic condition caused by germline mutations in the Dicer1 gene and predisposes to hereditary cancers such as pleuropulmonary blastoma, cystic nephroma, or differentiated thyroid carcinoma, among others." (PMID 39409030, 2024). "Historically known for its association with pleuropulmonary blastoma, DICER1 syndrome has received more attention due to the association with newly discovered diseases and tumors." (PMID 38254836, 2024). "A similar approach can be used for other tumors that are often hereditary, such pleuropulmonary blastoma caused by DICER1 mutations." (PMID 38803632, 2024). "The third case involves a child with pleuropulmonary blastoma and pediatric cystic nephroma/nephroblastoma, in whom a pathogenic variant in the DICER1 gene was identified." (PMID 37761810, 2023). "DICER1-related tumor predisposition was first described in families with pleuropulmonary blastoma, a rare pediatric lung tumor." (PMID 38084291, 2023). "Studies of pleuropulmonary blastoma and pituitary blastoma suggest greater than 80% specificity for an underlying pathogenic germline DICER1 variant, while cystic nephroma and Sertoli-Leydig cell tumors and gynandroblastoma appear to fall in the 60-80% range." (PMID 38084291, 2023). "In 2009, disease-associated variants in the DICER1 gene were first described in families with multiple cases of pleuropulmonary blastoma (PPB)." (PMID 34170462, 2021). "One study has reported the frequency of germline pathogenic variants in DICER1 in children with pleuropulmonary blastoma (PPB) to be 70 %." (PMID 34552563, 2021).
pleuropulmonary blastoma (continued). "DICER1 syndrome, characterized by germline truncating DICER1 mutations includes predisposition to pleuropulmonary blastoma and Sertoli–Leydig cell tumors." (PMID 32455595, 2020). "Some cases with somatic DICER1 mutations were also found to harbor a germline mutation in DICER1, predisposing to additional tumors including pleuropulmonary blastoma." (PMID 32485873, 2020). "In particular, germline mutations in DICER1 predispose individuals to multiple tumors, benign and malignant alike, including pleuropulmonary blastoma, cystic nefroma, embryonal rhabdomyosarcoma and multinodular goiter." (PMID 30956758, 2019). "The presence of such a germline mutation defines DICER1 pleuropulmonary blastoma familial tumor predisposition syndrome (FTPS)." (PMID 31349569, 2019). "A study on 11 pleuropulmonary blastoma patients revealed that, out of 11 patients with DICER1 gene mutations with sporadic pleuropulmonary blastomas, eight harbored biallelic DICER1 gene mutations in which one of the mutations was within the RNase IIIb domain." (PMID 29762508, 2018). "Mutations in the DICER1 gene are found in approximately 50–70% of pleuropulmonary blastoma patients." (PMID 29762508, 2018). "While treatments for pleuropulmonary blastoma and cystic nephroma have received wide attention from the scientific community, the root of these abnormal formations, DICER1 germline mutations and acquired somatic mutations, require more study." (PMID 29762508, 2018). "A cohort of individuals diagnosed with pleuropulmonary blastoma underwent analysis to determine the mutation status of DICER1 alleles." (PMID 29762508, 2018). "In this report we identify germ-line and somatic DICER1 gene mutations in a Caucasian family where two young females were diagnosed, one with cystic nephroma and pleuropulmonary blastoma, and the other with embryonal rhabdomyosarcoma and multinodular goiter." (PMID 28222777, 2017). "Germline mutations of DICER1 are associated with a range of human malignancies, including pleuropulmonary blastoma (PPB)." (PMID 24513630, 2014). "DICER1 mutations can cause a range of phenotypes from asymptomatic to various tumors such as cystic nephroma, pleuropulmonary blastoma, thyroid cysts, SLCTs, and Wilms tumor." (PMID 23193086, 2013). "Germline mutations in DICER1 have been identified in patients with pleuropulmonary blastoma, often associated with goiter and Sertoli-Leydig cell tumours." (PMID 23068969, 2012). "CN has been reported to be associated with pleuropulmonary blastoma and the DICER1 mutation." (PMID 35733141, 2022). "The DICER1 gene is associated with pleuropulmonary blastoma in children." (PMID 36476508, 2022). "Their study revealed six RMS patients among the 148 probands, and RMS was the fourth most commonly detected neoplasm amongst the DICER1 mutation carriers, behind pleuropulmonary blastoma (n = 47), Sertoli–Leydig cell tumor (n = 24), and thyroid cancer (n = 10)." (PMID 34065162, 2021). "Among these, DICER1 mutations were formerly known as germline mutations, which are associated with the so-called DICER1-syndrome and predispose carriers not only to multinodular goiter but also to pleuropulmonary blastoma, cystic nefroma and embryonal rhabdomyosarcoma." (PMID 30956758, 2019). "In addition, hereditary DICER1 loss-of-function mutations have so far been associated with pleuropulmonary blastoma." (PMID 30306785, 2018). "In addition, DICER1 mutations predispose to a rare type of lung cancer most often seen in children, known as pleuropulmonary blastoma." (PMID 24708902, 2014). "While thyroid tumors are the main tumors caused by this condition in adult oncology, children and adolescents with DICER1 germline mutations may suffer from a broader spectrum of tumors, including Sertoli-Leydig cell tumors, pleuropulmonary blastomas, embryonal rhabdomyosarcomas, and pineoblastomas." (PMID 40361440, 2025).
pleuropulmonary blastoma (continued). "Heterozygous germline mutations of DICER1 were first discovered in 2009 in a series of children with pleuropulmonary blastoma (PPB)." (PMID 40161378, 2025). "Although this tumor is rare in absolute numbers, it is perceived to be an important marker for DICER1 syndrome, as approximately 70% of children with pleuropulmonary blastoma (PPB) carry germline DICER1 mutations." (PMID 40361440, 2025). "We described three different DICER1 mutations; the two affecting the functionally relevant and frequently altered hotspots in the RNase IIIb domain have been already reported in thyroid lesions, whereas the DICER1_R459* has been previously identified only in pleuropulmonary blastoma." (PMID 37867524, 2023). "Germline DICER1 variants have been detected in individuals affected with familial pleuropulmonary blastoma (PPB), a rare malignant tumor of the lung, which occurs primarily in children under the age of 6 years." (PMID 33552988, 2020). "Germline or mosaic loss-of-function (LOF) DICER1 mutations predispose to DICER1 syndrome or pleuropulmonary blastoma (PPB) familial tumor and dysplasia syndrome, an autosomal dominant condition causing PPB and multiple other tumors." (PMID 32714280, 2020). "A nonsense germ-line mutation in DICER1 causing a truncated protein at the IIIb domain level was identified segregating within a family including two affected relatives who developed in one case cystic nephroma and pleuropulmonary blastoma, and rhabdomyosarcoma and multinodular goiter in the other." (PMID 28222777, 2017). "In general, DICER1 levels are decreased in different types of human tumors and germline mutations in DICER1 are associated with a rare type of childhood cancer called pleuropulmonary blastoma (PPB)." (PMID 26990999, 2016). "Ocular medulloepithelioma has been associated with a DICER1 germline mutations in familial pleuropulmonary blastoma (PPB) by genome-wide linkage analysis." (PMID 25807141, 2015). "There have been two reports of probable germline-associated DICER1s JCGTs: a patient with DICER1-related disorders presented with JGCT at the age of 16 and another patient whose second-degree cousin had pleuropulmonary blastoma developed JGCT at the age of 2." (PMID 40076617, 2025). "As of 2020, primary DICER1-related central nervous system sarcoma and primitive sarcoma similar to pleuropulmonary blastoma and DICER1-related renal sarcoma have been recognized." (PMID 40007992, 2025). "Germline mutations (i.e., inherited mutations from parents) in the DICER1 gene are associated with several rare hereditary tumor syndromes, such as DICER1 syndrome (also known as pleuropulmonary blastoma family tumor predisposition syndrome (PPB-FTPS))." (PMID 40226310, 2025). "Individuals with mutations in DICER1 are at an increased risk of developing RMS and many other cancer types, including pleuropulmonary blastoma (the highest cancer risk), cystic nephroma, thyroid cancer, and ovarian Sertoli–Leydig cell tumors." (PMID 34065162, 2021). "DICER1 variants have been associated with a syndrome involving familial pleuropulmonary blastoma (PPB), a rare malignant tumor of the lung, which occurs primarily in children under the age of 6 years and represents the most common life-threatening manifestation of DICER1 syndrome." (PMID 33552988, 2020). "DICER1 causes a cancer predisposition syndrome and DICER1 syndrome is an autosomal dominant genetic disorder characterized by pleuropulmonary blastoma (PPB), multinodular goiter, cystic nephroma, Sertoli–Leydig cell tumors of the ovary (SLCT), and other rare tumors." (PMID 33327492, 2020). "A murine study showed that mutations in the DICER1 gene leads to the formation of cystic airways, disruption of branching morphogenesis and mesenchymal expansion, features similar to pleuropulmonary blastoma (PPB)." (PMID 31249823, 2019).
pleuropulmonary blastoma (continued). "The DICER1 familial tumour susceptibility syndrome confers an increased risk most commonly for pleuropulmonary blastoma (PPB) but also ovarian sex cord-stromal tumours; Sertoli-Leydig cell tumor [SLCT], juvenile granulosa cell tumour [JGCT] and gynandroblastomas." (PMID 26138824, 2015). "Similarly, pleuropulmonary blastoma (PPB) may be the first clinical manifestation in individuals with germline DICER1 mutations, which predispose to a range of neoplastic conditions." (PMID 40868080, 2025). "Germline pathogenic variants in DICER1 cause a tumour predisposition syndrome (OMIM 601200), which is characterized by occurrence of pleuropulmonary blastoma, Sertoli-Leydig cell tumour, cystic nephroma, multinodular goiter, embryonic rhabdomyosarcoma of the cervix uteri and other tumour types." (PMID 34331184, 2023). "Pleuropulmonary blastomas (PPB) are rare aggressive paediatric lung malignancies and are among the most common DICER1-related disorders: it is estimated that 75–80% of children with a PPB have the DICER1 mutation." (PMID 33028416, 2020). "Interestingly, uterine ERMS may develop in connection with the pleuropulmonary blastoma (PPB) familial tumor predisposition syndrome, which is characterized by germline mutations in DICER1 (DICER1 syndrome)." (PMID 33846547, 2021). "Pleuropulmonary blastomas (PPB) are sarcomatous malignant pediatric tumors of the lung parenchyma and pleural surfaces which fall under the larger aegis of the DICER1-related disorders." (PMID 31349569, 2019). "Pleuropulmonary blastomas (PPB) are pediatric, embryonal cancers of the lung parenchyma and pleural surfaces and are among the most common DICER1—related disorders." (PMID 31349569, 2019).